TRIM21 (tripartite motif containing 21)
Diseases named in the same sentence as TRIM21 in open-access papers (continued):
Sharing a sentence is not in itself a finding about the gene and the disease.
tumor (131 papers, 2011 to 2026). "Analysis of ESCC tumor samples revealed that reduced TRIM21 expression is associated with poorer patient prognosis." (PMID 40652518, 2025). "In contrast, the E3 ligase TRIM21 accelerates tumor progression in vitro and in vivo through K63-linked polyubiquitination of β-catenin, leading to its nuclear translocation via the Wnt/β-catenin signaling pathway." (PMID 39039049, 2024). "Collectively, these findings demonstrate that TRIM21 deficiency in tumour cells results in enhanced IR-induced antigen presentation." (PMID 36797289, 2023). "Flow cytometry revealed that TRIM21 deficiency increased the proportion of CD40+ CD11c+ tumour-infiltrating DCs." (PMID 36797289, 2023). "In patients with NPC, high TRIM21 expression was associated with poor prognosis and early tumour relapse after radiotherapy." (PMID 36797289, 2023). "Tripartite motif-containing protein 21 (TRIM21), a member of the ubiquitin ligase family, makes a significant contribution to the ubiquitination of multiple tumor marker proteins associated with tumor cell proliferation, metastasis and selective apoptosis." (PMID 37335642, 2023). "Surprisingly, we observed a significant growth delay of abscopal tumours in mice bearing primary TRIM21-deficient tumours after radiation treatment compared to the abscopal tumours in mice bearing primary WT tumours." (PMID 36797289, 2023). "The percentages of infiltrating CD45+ cells, CD3+ T cells, CD8+ T cells, and CD69+ CD8+ T cells were increased in irradiated TRIM21-deficient tumours." (PMID 36797289, 2023). "Besides, TCF3 knockdown partially restored tumor growth restriction caused by TRIM21 downregulation in vivo, and the corresponding results of IHC staining were also obtained." (PMID 40998798, 2025). "TRIM21 forms a complex with the β-catenin upstream regulator, TIF1γ, in the nucleus and accelerated its degradation by inducing K48-linked ubiquitination at K5 site, to increase the level of nuclear β-catenin for tumor proliferation." (PMID 40735642, 2025). "Similarly, TRIM21 deficiency was associated with reduced tumour growth and a lower weight of the excised tumours after IR treatment." (PMID 36797289, 2023). "Furthermore, both depletion of CD8+ T cells and IFNAR1 blockade abolished the growth retardation of TRIM21-deficient tumours after radiation treatment." (PMID 36797289, 2023). "Moreover, CD8+ T cells in TRIM21-deficient tumours expressed higher levels of IFN-γ and TNF after stimulation with phorbol 12-myristate 13-acetate (PMA) and ionomycin." (PMID 36797289, 2023). "Collectively, these results suggest a potential pathway wherein propofol activated GABAAR, which caused downregulation of TRIM21 and consequent upregulation of Src, leading to enhancement of adhesion and extension of the tumor cells with VECs, potentially promoting tumor metastasis." (PMID 34263559, 2021). "TRIM21 could catalyze the K63-linked polyubiquitination on programmed cell death-1 (PD-1) at K233, resulting in stabilization of PD-1 by antagonizing its K48-linked polyubiquitination and degradation to impair anti-tumor immunity of CD8+T cells." (PMID 40735642, 2025). "To test the functional link between Sugt1 and Trim21, we realized that Trim21 has been reported to catalyze p21 ubiquitination and degradation with its E3 ubiquitin ligase activity and Trim21 deficiency is highly related to tumor cell proliferation and cellular senescence." (PMID 39872547, 2023). "Thus, it is tempting to speculate that the pathology IgGs might contribute to the degradation of specific targets via its association of TRIM21 in tumor cells." (PMID 32580738, 2020). "In conclusion, this study reveals the GIPC1/TRIM21/TTC7B/mTOR/NF-κB tumor-suppressive axis in CRC and highlights the potential of GIPC1 for early diagnosis and overcoming chemoresistance in CRC patients." (PMID 41522336, 2026).
tumor (continued). "The complex regulatory network of TRIM21 suggests its great potential as a tumor therapeutic target, but its “double-edged sword” characteristics need to be overcome in the future." (PMID 40735642, 2025). "TRIM21 overexpression significantly suppressed tumor growth in mouse xenograft model, which was completely rescued by the restored expression of METTL3." (PMID 40175350, 2025). "Taken together, TRIM21 changes its oncogenic and tumor-suppressive roles depending on its binding targets." (PMID 40723250, 2025). "IHC staining was also performed on the subcutaneous tumor tissue to analyze the expression of TRIM21, PRMT1, and Ki-67." (PMID 39890802, 2025). "The combination therapy greatly suppressed tumor growth in TRIM21 overexpression tumors, but the therapeutic efficacy of immunotherapy was significantly impaired in METTL3 high expression tumors." (PMID 40175350, 2025). "TRIM21-mediated METTL3 ubiquitination as a critical regulator of ferroptosis to prevent tumor progression." (PMID 40175350, 2025). "In terms of tumor motility, transwell analysis demonstrated that TRIM21 knockdown promoted the migration and invasion ability of CRC cells, while TRIM21 overexpression inhibited these abilities." (PMID 39890802, 2025). "TRIM21 functions as tumor-promoting effects in certain malignancies and tumor-suppressive functions in others." (PMID 40809696, 2025). "TRIM21-regulated ferroptosis exerts remarkable influence on tumor progression and therapeutic strategies." (PMID 40175350, 2025). "Our data provides compelling evidence that hypoxia-mediated stabilization of ID1 exacerbates these tumor-promoting effects, while TRIM21 knockdown mitigates ID1-driven oncogenicity." (PMID 40919143, 2025). "This work further performs loss‐ and gain‐of‐function assays for TRIM21, revealing that TRIM21 knockout inhibits tumor proliferation and gemcitabine resistance both in vitro and vivo." (PMID 39739616, 2025). "In summary, TRIM21 promotes tumour growth and gemcitabine resistance in PC by inhibiting EPHX1‐mediated arachidonic acid metabolism." (PMID 39739616, 2025). "Further in vitro and in vivo experiments confirmed the tumor suppressor role of TRIM21 in inhibiting CRC proliferation and metastasis." (PMID 39890802, 2025). "Collectively, the specific roles of TRIM21 in modulating tumor metabolism, especially lipid metabolism, and its interaction with metabolic networks require further exploration." (PMID 40735642, 2025). "Immunohistochemical analysis revealed significant downregulation of TRIM21 in ESCC tumor tissues compared with matched adjacent normal epithelia." (PMID 40652518, 2025). "We found that knockdown of ID1 significantly suppressed tumor growth, whereas silencing TRIM21 led to accelerated tumor progression." (PMID 40919143, 2025). "This is equivalent to the result of treatment with the ferroptosis inhibitor Ferrostatin-1, which led to substantial rescue of tumor growth suppressed by TRIM21 overexpression, indicating that ferroptosis was indeed involved in TRIM21-regulated tumor growth." (PMID 40175350, 2025). "Recent studies have revealed that TRIM21 acts as a tumor suppressor in multiple cancers by targeting and degrading oncoproteins to modulate tumor progression." (PMID 40919143, 2025). "The E3 ligase TRIM21 mediated K48-linked polyubiquitination of METTL3 at the K459 site, leading to the proteasomal degradation of METTL3, which prevented tumor progression by promoting ferroptosis." (PMID 40175350, 2025). "Further studies to explore the interaction between the additional targets and the STAMBPL1/TRIM21/AXL axis will expand the understanding of the function of STAMBPL1 in tumor progression." (PMID 39527690, 2025).
tumor (continued). "It has been reported that TRIM21 participates in sustaining cell proliferation, autophagy, tumor proliferation, metastasis and anti-tumor immunity." (PMID 40735642, 2025). "In this review, we provided an in-depth understanding of the specific mechanism of TRIM21 in different biological processes and tumor types, which contributes to the development of novel targeted therapeutic strategies targeting TRIM21." (PMID 40735642, 2025). "For example, tripartite motif-containing protein 21(TRIM21) functions as a ubiquitin ligase that directs proteasomal degradation of CD73 in tumor cells." (PMID 41583489, 2025). "This indicates that the oncogenic effects of hypoxia are at least partially mediated by TRIM21 downregulation, and underscores TRIM21 as a key modulator of hypoxia-adaptive tumor behavior via post-translational control of ID1." (PMID 40919143, 2025). "Both aberrant upregulation and downregulation of TRIM21 in tumor tissues has been found to be correlated with adverse clinicopathological characteristics and poor prognosis, suggesting its potential as a context-dependent prognostic biomarker." (PMID 40735642, 2025). "TRIM21 plays a pivotal role in tumor growth and chemoresistance by regulating EPHX1‐mediated arachidonic acid metabolism." (PMID 39739616, 2025). "In summary, our study comprehensively explored the role of miR-99a-3p in GC, revealing its association with unfavorable patient outcomes, functional implications in tumor progression, and a direct regulatory relationship with TRIM21." (PMID 38720056, 2025). "This functional duality—tumor suppressive through inhibition of Ras signaling in some tissues, and oncogenic through TRIM21–GMPS stabilization in others—illustrates the deep context dependence of snoRNA–protein interactions in cancer." (PMID 41375049, 2025). "In pancreatic ductal adenocarcinoma, TRIM21 was upregulated in PDAC samples compared with non-tumor samples." (PMID 40735642, 2025). "To determine if TRIM21 functions in a PRMT1-dependent manner, we restored the expression of PRMT1 in the OE-TRIM21 group, which reversed the tumor-inhibiting effect of TRIM21." (PMID 39890802, 2025). "Clinical samples from the study showed that reduced TRIM21 expression correlated with advanced tumor stages, higher recurrence rates, and poor survival outcomes." (PMID 39768197, 2024). "Inhibiting CDK5 expression promotes TRIM21-mediated PD-L1 degradation, enhancing anti-tumor immunity." (PMID 39223632, 2024). "Results showed that reducing USP7 expression decreased the metastasis of tumor cells in Zebrafish, while downregulating TRIM21 increased tumor metastasis and reversed the inhibition of metastasis caused by shUSP7 cells." (PMID 38702792, 2024). "Conversely, there are still some reports indicating that TRIM21 can inhibit the autophagy process in tumor cells." (PMID 38783335, 2024). "While HUWE1, UBR5, PRPF19, ARIH2 and OBI1 are mainly related to tumor suppression, DNA damage response and DNA replication, TRIM21 is involved in regulating host innate immunity and viral immune evasion." (PMID 38932241, 2024). "Downregulation of USP7 expression significantly suppressed tumor growth in mice, whereas reduced TRIM21 expression promoted xenograft tumor growth." (PMID 38702792, 2024). "Except for NLRP4 and TRIM21, the expressions of the remaining 13 genes between normal and tumorous tissues differed significantly." (PMID 39185402, 2024). "The underlying details of interplay between TRIM21 and OTUD4 in determining cellular CD73 abundance modulating tumor immune responses in the context of tumor progression awaits further investigation." (PMID 38530357, 2024).
tumor (continued). "The overexpression of TRIM21 in tumor cells reduces adenosine production, resulting in increased expression of IFN-γ and promoting T-cell proliferation." (PMID 39223632, 2024). "These seemingly contradictory observations limit the utility of TRIM21 as a potential target for tumor therapy." (PMID 39152265, 2024). "Evidence shows that antibodies can be internalized by the tumor cells through AP2, important for clathrin-mediated endocytosis, and once inside the tumor cell, they can bind to the target via Fab, and to TRIM21 via the Fc receptor." (PMID 39086481, 2024). "TRIM21 plays an important role in proliferation and apoptosis of tumour cells and has been proposed as a potential target for therapy." (PMID 39159071, 2024). "We also found a decrease observed in the tumours of the 4T1Cct6a+Trim21 mouse group compared with those in the 4T1Cct6a+Trim21‐ΔRING mouse group." (PMID 39556022, 2024). "Research has shown that various key tumor suppressors or oncogenes can serve as substrates for TRIM21-mediated ubiquitination, playing crucial roles in malignant behaviors like proliferation and metastasis in multiple cancers." (PMID 38702792, 2024). "Current research is centered on augmenting the immune response provoked by RT, potentially through inhibiting the tumor-intrinsic E3 ligase tumor cell-intrinsic tripartite motif-containing 21 (TRIM21), to further bolster antitumor immunity." (PMID 39165639, 2024). "Low TRIM21 expression was significantly positively correlated with tumor size (p = 0.001), lymph node metastasis (p = 0.004), and distant metastasis (p = 0.001)." (PMID 36694250, 2023). "Functionally, high expression of wild-type TRIM21 accelerates tumor progression in vitro and in vivo, whereas TRIM21 mutants, including one with a critical RING-finger deletion, do not." (PMID 37771771, 2023). "The present study also confirmed the role of TRIM21 as a tumor suppressor in TNBC and its key role in mediating the combined therapeutic effect of Sorafenib and Olaparib." (PMID 37864041, 2023). "Collectively, these results are consistent with the previous studies that TRIM21 acts as a tumor suppressor in TNBC." (PMID 37864041, 2023). "In summary, our study reveals that the tumour cell-intrinsic E3 ligase TRIM21 inhibits radiation-initiated, VDAC2 dependent, and mtDNA-induced STING–type-I IFN signalling and antitumour immune responses in NPC." (PMID 36797289, 2023). "Consistent with the findings in the tumor studies, TRIM21 mediates FASN ubiquitination and degradation in hepatocytes." (PMID 37249651, 2023). "In cancerous diseases, TRIM21 has been shown to facilitate tumor lipid metabolism via mediating ubiquitination and degradation of fatty acid synthase (FASN), one of the rate-limiting enzymes in the de novo lipogenesis pathway." (PMID 37249651, 2023). "Compared to TRIM21-WT tumours, TRIM21-KO tumours displayed obvious growth retardation following IR treatment." (PMID 36797289, 2023). "TRIM21/Ro52 has a dual role in cancers, as it can promote or suppress tumor growth depending on cancer cell types." (PMID 37993883, 2023). "Here, we investigated the role of TRIM21 as a biomarker candidate for HNSCC in predicting tumor progression and patient survival." (PMID 36982215, 2023). "Subsequent flow cytometric analysis confirmed that the expression of surface MHC class I molecules on SUNE1 and MC38 cells was significantly increased in TRIM21-KO tumours after IR treatment." (PMID 36797289, 2023). "We further performed IHC staining in a cohort of 355 paraffin-embedded NPC samples and found that NPC patients who developed locoregional recurrence had higher TRIM21 expression levels than those who remained tumour-free." (PMID 36797289, 2023). "The results revealed that tumours with higher TRIM21 or lower VDAC2 expression levels were infiltrated with fewer CD3+ CD8+ T cells and CD11c+ DCs, indicating weaker antitumour immunity." (PMID 36797289, 2023).
tumor (continued). "Here, we found that tumour-intrinsic E3 ligase TRIM21 inhibited radiation-induced mtDNA release and limited antitumour immunity in NPC." (PMID 36797289, 2023). "IHC staining of tumor xenografts showed that TRIM21 overexpression markedly increased β-catenin expression, which was reduced by TIF1γ overexpression, which was also observed in Ki-67 index respectively." (PMID 37771771, 2023). "Collectively, our results demonstrate that high TRIM21 expression indicates a poor antitumour immune response within NPC tumours, as well as a poor survival prognosis and a high likelihood of relapse in NPC patients." (PMID 36797289, 2023). "Collectively, these results suggested that TRIM21 protected tumor cells against ferroptosis by promoting FSP1 ubiquitination at K322 and K366." (PMID 37587773, 2023). "While this TRIM21-based bioPROTAC elicits specific HuR degradation with limited TRIM21-mediated effects, the most striking observation is the rapid and sustained tumour growth arrest in vivo." (PMID 37925433, 2023). "These in vitro–based findings suggest a tumor-suppressor role of TRIM21 by inhibiting metabolic pathways that fuel nucleic acid synthesis, cell growth, and proliferation." (PMID 37937648, 2023). "TRIM21 can not only regulate tumor metabolic process, immune function and tumor treatment, it is also a useful cancer prognostic indicator, but the cancer type needs to be defined." (PMID 36159815, 2022). "Although TRIM21 is increasingly important in tumor progression, there are several issues that require attentions." (PMID 36159815, 2022). "This RAC1 activity is normally inhibited on a soft ECM, thereby also suppressing glycolysis and perhaps supporting the TRIM21 tumor suppressive mechanism explained above." (PMID 36140753, 2022). "Tumours have been known to over-express Ro52/TRIM21, being a source of neo-antigens for antibodies to develop." (PMID 35871174, 2022). "The detailed mechanisms of TRIM21 in maintaining the balance of tumor metabolism, especially in lipid metabolism, and the cross-talk between metabolic activities merit further research." (PMID 36159815, 2022). "We found that propofol activated GABAAR to decrease expression of TRIM21 and increase expression of Src, which enhanced tumor cell adhesion and extension, leading to promote tumor metastasis in lungs of mice." (PMID 34263559, 2021). "First, we did not inject the GABAAR knockout or TRIM21 overexpression HCT116 cells into the mice to further determine the role of GABAAR or TRIM21 in the propofol‐promoted tumor metastasis in vivo." (PMID 34263559, 2021). "TRIM21 suppresses progression of tumor metastasis by ubiquitylation and degradation of Snail and IκB kinase β." (PMID 34263559, 2021). "The dysregulation of TRIM21 contributes to the progression of human malignancies including breast cancer." (PMID 32102992, 2020). "TRIM21 expression is correlated with prognosis, which acts as a tumor suppressor in patients with GBM." (PMID 33193404, 2020). "In this regard, TRIM21 functions as a tumour suppressor, as FASN is overexpressed in various types of cancer." (PMID 32225170, 2020). "Increased PPP activity in the TRIM21 knockout cells also led to increased cell growth and tumor volume in vitro and in vivo, respectively, demonstrating the important role of TRIM21 in negatively regulating the PPP and cell growth." (PMID 32312982, 2020). "However, the mechanism underlying TRIM21-regulated tumor development is unknown." (PMID 29038421, 2017). "Knockdown of SAE2 reduced Oct-1 and increased TRIM21 protein levels in mouse xenograft tumour tissues as shown by IHC staining." (PMID 27465491, 2016).